IL13 (interleukin 13)
Diseases named in the same sentence as IL13 in open-access papers (continued):
Sharing a sentence is not in itself a finding about the gene and the disease.
asthma (continued). "S100A8 and S100A9 can promote mucus hypersecretion typical of asthma in BECs, which is consistent with our previously published works documenting reduced MUC5AC post-BT along with IL-13+ cells in bronchial biopsies collected from a similar cohort." (PMID 37996952, 2023). "From experimental results, we found that stigmasterol inhibited oxidative stress and inflammation response in IL-13-induced BEAS-2B cells and asthma mice by NK1-R." (PMID 36788676, 2023). "Biologics targeting IgE, IL-4, IL-5, IL-13, and TSLP are used for uncontrolled severe asthma; their targets are all mediators produced by cells in the microenvironment of ILC2s." (PMID 36941691, 2023). "Increased secretion of Th2-type cytokines, such as IL-4, IL-5, and IL-13, in the allergic airway results in increased recruitment of inflammatory cells and airway hyperresponsiveness, suggesting that airway inflammation may be related to the severity of asthma." (PMID 36717898, 2023). "Xiaoqinglong decoction was reported to have an inhibitory effect on airway remodeling in the lung tissues of mice with asthma by suppressing the expression of TGF-β1 and IL-13." (PMID 38074219, 2023). "A recent study highlighted the major contributions of Th2 cytokines, such as IL4, IL13, and IL5, to asthma, while interferon-γ, a Th1 cytokine, has recently been shown to maintain the chronic inflammatory response in asthma." (PMID 37191813, 2023). "In CRS, as well as in asthma, the activation of ILC-2 cells leads to the release of cytokines (Il-9, Il-4, Il-5, and IL-13) that promote a Th-2 inflammatory response." (PMID 37947596, 2023). "In CRS, as in asthma, the activation of ILC-2 cells leads to the release of cytokines (Il-9, Il-4, Il-5, and IL-13) stimulating a Th-2 inflammatory response." (PMID 37108417, 2023). "IL-13 also plays a major role in the secretion of periostin (POSTN), which is an essential biomarker in asthma." (PMID 36832296, 2023). "A study investigating asthma-mediated protection from SCV2 infection reported higher keratinization of the cells, mediated through IL-13 signaling, to be a mechanism of protection against high viral loads." (PMID 36986402, 2023). "Such structural effects are at least in part mediated by the IL-13-dependent induction of transforming growth factor-β1 (TGF-β1), a fibrogenic mediator which crucially contributes to airway remodeling in asthma." (PMID 37240477, 2023). "Dupilumab, a monoclonal antibody that inhibits the action of IL-4 and IL-13 by blocking the shared IL-4 receptor α subunit has been approved by the FDA for moderate–severe atopic dermatitis, asthma, and rhinosinusitis with nasal polyposis treatment." (PMID 37765327, 2023). "In asthma, HMGB1 expression induces HSP expression through the TLR4 / MYD88 / NF-kB pathway, which eventually produces IL-4 and IL-13." (PMID 37422662, 2023). "Biologic agents targeting inflammatory cytokines, comprising anti-immunoglobulin (Ig)E and anti-interleukin (IL)-4/IL-13, IL-5, IL-5R, and thymic stromal lymphopoietin (TSLP) have emerged as promising treatment options for patients with severe asthma." (PMID 36845128, 2023). "IL-5 and IL-13 secretion was analyzed by ELISA, and again, the two TH2 cytokines were elevated in asthma groups, but the amounts of secreted cytokines were similar in the asthma groups." (PMID 37443808, 2023). "IL-33 production induces IL-13 production in ILC-2 cells, and TH2 cytokine-producing cells promote allergic inflammation in the experimental animal models of asthma and atopic dermatitis." (PMID 37685567, 2023). "Treatment of ferrostatin-1 (Ferr-1) and 3-methyladenine (3-MA) decreased iron deposition in IL-13-induced BEAS-2B cells and lung tissues of asthma mice, opposite to that in bronchoalveolar lavage fluid (BALF)." (PMID 35154576, 2022). "For all participants with asthma and COPD, mMRC and IL-13 were found to have significant differences after treatment." (PMID 35677382, 2022).
asthma (continued). "In an experimental asthma rat model, CBD diminished airway inflammation and IL-4, IL-5, IL-13, IL-6, IL-7 and TNF-α serum levels, which contribute to fibrosis and asthma pathophysiologies." (PMID 36556483, 2022). "In asthma, allergic airway inflammation is initiated by IL-33 signaling through ST2, leading to increased IL-4, IL-5, and IL-13 production and eosinophil infiltration." (PMID 35025767, 2022). "The IL-4/IL-13/STAT6 pathway induces expression of inflammatory chemokines such as CCL11, CXCL1, and CXCL3 and is a central pathway in the pathophysiology of asthma, especially airway hyperresponsiveness." (PMID 35281012, 2022). "IL-5 levels were significantly higher in patients with asthma and ABPA than in those with CPA (p < 0.05), and IL-13 levels were significantly higher in patients with asthma than in those with CPA (p < 0.05)." (PMID 35628692, 2022). "Therapies targeting mast cell mediators and/or their receptors, including monoclonal antibodies targeting IgE, IL-4/IL-13, IL-5/IL-5Rα, IL-4Rα, TSLP, and IL-33, have been found safe and effective in the treatment of different phenotypes of asthma." (PMID 36430941, 2022). "MAPK pathway is correlated with some inflammatory responses of patients with asthma, such as the release of inflammatory proteins TGF-β1 and IL-13." (PMID 36184652, 2022). "In the HDM-induced mouse asthma model, we found that the HDM extract promoted airway hyperresponsiveness (AHR), MUC5AC, and allergen-specific IgE production as well as IL-5 and IL-13 for recruiting inflammatory cells." (PMID 36012669, 2022). "It is well-known that IL-4, IL-5, and IL-13 cytokines produced by CD4+ natural killer T cells and CD4+ T MHCII-restricted cells enhance eosinophilia and increase the severity of asthma." (PMID 35733161, 2022). "In conclusion, this study shows that the expression of CLCA1 and IL-13 was positively correlated in pediatric asthma, and that knockdown of CLCA1 attenuated the IL-13-induced decreased activity and apoptosis of bronchial epithelial cells." (PMID 36313877, 2022). "The level of production of IgE, IL-4, IL-5, IL-13, and IFN-γ is related to the severity of asthmatic symptoms in T2 asthma." (PMID 36430662, 2022). "Plasma miR-206, IL-4, IL-13, and INF-γ have been found to have potential prognostic value in asthma-induced pulmonary arterial hypertension." (PMID 36459329, 2022). "To simulate the condition of HBSMCs during asthma remission, we established a sensitive HBSMC model by using 100 ng mL−1 IL‐13 and found that sensitive HBSMCs exhibited increased eotaxin expression." (PMID 34816611, 2022). "Asthma is an inflammatory disease characterized by AHR, the production of Th2 inflammatory cytokines (IL-4, IL-5, and IL-13), and the increased infiltration of inflammatory cells into the airways that results from the activation of Th2 cells." (PMID 36311189, 2022). "In order to explore the relationship between the expression of IL1-RL1 in sputum supernatant of patients with asthma and type 2 inflammation, we analyzed the correlation between IL1-RL1 and Th2 inflammatory factors, such as IL-4, IL-5, IL-10 and IL-13." (PMID 35578178, 2022). "Increases in IL-13 level and neutrophil ratios in BAL were moderately correlated with the abundance of bacteria in BAL in patients with asthma, suggesting involvement of IL-13 in the remodeling of airways under inflammation due to bacteria." (PMID 36291665, 2022). "When activated by FcεRI, mast cells release IL-1β, IL-6, IL-13, and TNF-α, which are involved in the pathology of asthma." (PMID 35266441, 2022). "It has been shown that plasma miR-206, IL-4, IL-13, and INF-γ has potential significance for prognosis of asthma-induced pulmonary arterial hypertension." (PMID 36459329, 2022).
asthma (continued). "Membrane localization of SLC26A9 was enhanced in wtCFTR-expressing CFBE airway epithelial cells by the interleukin IL-13, which corresponds to earlier data suggesting upregulation of SLC26A9 function in mouse airways by IL-13 and possibly in asthma." (PMID 35328418, 2022). "In our HDM-induced asthma model, we found that PEP-NASP peptide treatment markedly ameliorated AHR and reduced the production of type two inflammatory cytokines (IL-5 and IL-13) and MUC5AC." (PMID 36012669, 2022). "In BALB/c-OVA model of asthma, the HIF-1α antagonist YC-1 suppressed HIF-1α expression and lowered the transcript levels of IL-5, IL-13, myeloperoxidase, and NOS2." (PMID 35453294, 2022). "The therapeutic treatment of asthma involves the use of corticosteroid inhalers, bronchodilators, leukotriene modifiers and anti-E, anti–IL5, anti–IL4/IL13 antibodies, coupled with lifestyle modifications to reduce the exposure to environmental allergens." (PMID 36264868, 2022). "One cell type that also produces IL‐5 and IL‐13 in response to IL‐33 is the mast cell, and as TGF‐β has been shown to suppress IL‐33–induced mast cell function in the context of asthma, this population is a prime candidate for further investigation." (PMID 35758054, 2022). "In Th2-high asthma, MAPK promotes Th2 cells to release IL-4, IL-5, and IL-13, stimulating IgE production, eosinophil recruitment, and airway hyperresponsiveness." (PMID 35447890, 2022). "Consistently, we detected IL-4, IL-5, IL-13, IL-25, IL-10, IL-33, and TSLP in induced sputum of asthma and proved a positive correlation between BIRC3 and these cytokines." (PMID 35287655, 2022). "In T2-high asthma, clinical symptoms result from inflammation driven by the cytokines interleukin-4 (IL4), IL5, and IL13, as well as alarmins [thymic stromal lymphopoietin (TSLP), IL25, IL33] and Immunoglobulin E (IgE)." (PMID 36237537, 2022). "It is generally accepted that the Th2 cytokines such as IL-4 and IL-13 lead to allergic asthma phenotype, and studies have shown that OVA-induced asthma in mice is often accompanied by a significant increase in Th2 cytokine levels." (PMID 35281601, 2022). "CAD significantly decreased the content of TNF-α, IL-13, IL-4, IL-1β and IL-5 in the bronchoalveolar lavage fluid (BALF), IL-17, IL-6, and OVA-specific IgE in serum and increased serum IFN-γ in asthma mice." (PMID 36213326, 2022). "IL-4 and IL-13, the cytokines upstream of STAT6, increased in human asthma, and clinical trials targeting the IL-4/IL-13/STAT6 pathway are ongoing." (PMID 35204186, 2022). "Mice with asthma induced by house dust mites and treated with anti-IL-13 therapy show reduced AHR, and AHR cannot be triggered in knockout IL-13 mice with induced asthma." (PMID 35682783, 2022). "In this study, we established the mouse asthma model following the ovalbumin (OVA) method in C57BL/6 mice and the cell model with IL-13 induction in bronchial epithelial cells (BEAS-2B cells)." (PMID 35154576, 2022). "The levels of IL-4, IL-5, IL-13, IFN-γ, eotaxin, and IgE in the asthma group were significantly higher than those in the control group." (PMID 35990822, 2022). "In line with that, simultaneous induction of IL-13 and IL-17A led to pronounced airway hyperresponsiveness (AHR) in a mouse model of experimental asthma." (PMID 35883573, 2022). "Asthma‐2 (n = 19) combined a pro‐inflammatory signature, with a Th2 and innate immune response with upstream modulators of IL‐1β, TNF, IL‐13, IL‐15, and IFNγ." (PMID 34962717, 2021). "Alternative to anti-IL13 antibodies, IL4Rα antagonists (dupilumab) have been recently FDA approved as add-on-maintenance therapy to treat moderate-to-severe asthma." (PMID 34305924, 2021). "Increased release of Th2 cytokines mainly IL-4, IL-5, and IL-13 and decreased release of IFN-γ as a Th1 cytokine also contribute in the onset and progression of asthma." (PMID 34804178, 2021).
asthma (continued). "Th2 cytokines, such as IL‐4 or IL‐13, contribute to the development of inflammation in the lungs of OVA‐induced murine asthma model by promoting differentiation of macrophages into alternatively activated M2 macrophages." (PMID 33945658, 2021). "In order to assess the alleviating effect of BV on asthma, we examined the effect of BV on the phosphorylation of STAT6 in A549 cells treated with IL-13." (PMID 34822557, 2021). "Because Th2 cytokines, including IL-13 and IL-4, act on goblet cell hyperplasia, fibroblast-to-myofibroblast transformation, collagen deposition, and airway smooth muscle contraction, high FeNO levels in patients with severe asthma may be affected by airway remodeling." (PMID 35008504, 2021). "Asthma is driven by group 2 innate lymphoid cells, antigen-specific CD4+ T helper type 2 cells and their cytokines such as interleukin (IL)-4, IL-5, IL-13." (PMID 34516405, 2021). "Treatment of the asthmatic rats with evodiamine prevented this increase, with IL-4, IL-13, and IL-17 levels in BALF, relative to the asthma group." (PMID 33577738, 2021). "IL-13, a type-2 cytokine, has been shown to downregulate the expression of ACE2 on airway epithelial cells in asthma and allergic rhinitis." (PMID 34945846, 2021). "In the BAL IL‐13 tertiles, severe asthma patients with high BAL IL‐13 and those with low BAL IL‐13 were similar in terms of demographics and were treated with similar doses of inhaled corticosteroids." (PMID 33411348, 2021). "Amongst these genes, we find IL13 and its receptor IL13RA1 which are known the be driving the mucus hypersecretion phenotype in asthma." (PMID 33731770, 2021). "Therefore, targeting JMJD2B may help alleviate IL-13-mediated biological responses in asthma." (PMID 33688506, 2021). "The biomarkers suspected to be most indicative of asthma are related to inflammation (type 2) and are attributed to TH2-cytokines, IL-4, IL-5, and IL-13." (PMID 34712855, 2021). "CP and OA were shown to significantly inhibit airway and lung inflammation, mucus secretion, lymphocytes, neutrophil and eosinophil infiltration, AHR, and inflammatory mediators such as IL-5, IL-13, CCR3, MUC5AC, and COX-2 in the mouse model of asthma." (PMID 33806085, 2021). "Mechanistically, the pathological role of PI3Kγ in asthma implicates the release of inflammatory cell mediators, including macrophage migration inhibitory factor (MIF) and the T-helper type II cytokine Interleukin-13 (IL-13)." (PMID 33821232, 2021). "In a mouse model of asthma, IL-25-induced ILC2s and IL-33-induced ILC2s contributed 50~80% of the total IL5 and IL-13 production in the lung, although stimulation with IL-25 or IL-33 separately did not cause excessive lung reactions." (PMID 34177881, 2021). "In the pathogenesis of asthma, CD4+ T cells synthesize proinflammatory cytokines such as IL-4, IL-5 and IL-13." (PMID 34209324, 2021). "IL-5 and IL-13 showed strong correlations with AHR and CCL2 (MCP-1) in asthma severity and fast lung function decline." (PMID 33806085, 2021). "PBM presents significant and effective results in the reduction of eosinophils, production of IL-4, IL-5, and IL-13 in BAL, airway remodeling, and lung function in asthma." (PMID 35185864, 2021). "CLCA1 is also one of the 6 genes (CLCA1, IL4, IL13, MMP12, TGFB1, TLR4) found in common between our KE genesets and the genesets proposed by Bosse24 for COPD and Poole27 for asthma." (PMID 33731770, 2021). "Th2 cytokines, especially IL-5 and IL-13, are decreased by miR-146a on ILC2 by inhibiting IRAK1, and miR-146a also alters neutrophil migration from bronchial epithelial cells in asthma." (PMID 34566492, 2021). "Extreme group analysis of the severe asthma patients, defined by BAL IL‐13 tertiles, once again demonstrate worse disease in high BAL IL‐13 patients with worse lung function." (PMID 33411348, 2021). "Our finding demonstrates this to be true for some severe asthma patients, identified as the low BAL IL‐13 group." (PMID 33411348, 2021).
asthma (continued). "Type 2-driven asthma is a subtype of asthma in which there is a notable release of interleukin-4 (IL4), IL5, and IL13 from cells of both innate and adaptive immune systems." (PMID 34575604, 2021). "It was shown that Th2 cytokines, such as IL-4, IL-5, and IL-13, together with eotaxin/CCL11, regulate critical aspects of eosinophil recruitment, allergic inflammation, and airway hyperresponsiveness in asthma." (PMID 33806927, 2021). "Given that the Th2 cytokines (IL-4 and IL-13) are reduced in the lungs of GRK2+/− mice, it is possible that GRK2 modulates T cell responses during asthma." (PMID 35386975, 2021). "MicroRNA-21 has been shown to be induced by IL-13, which is critically responsible for airway hyperreactivity, in the ovalbumin (OVA) murine model of asthma." (PMID 32641036, 2020). "In Th2 group asthma patients, CD4+ T cells produce IL-4, IL-5, and IL-13 (Th2 cells), which have been reported in bronchoalveolar lavage and airway autopsies." (PMID 32770056, 2020). "Sema4D can directly increase TGF-β1 expression, and IL-13 and TGF-β1 expression was decreased in a Sema4D −/− mouse model of experimental asthma." (PMID 32944173, 2020). "The upstream regulator cytokines of S1P signaling such as IL-13, IFN-γ, TNF-α, IL-4, IL-5, and IL-1β were significantly (P < 0.01) increased in the serum of asthma patients compared the healthy controls." (PMID 32637407, 2020). "In patients with asthma, excessive Th2 cell activation increases AHR; indeed, IL-13 is a pleiotropic Th2 cytokine that induces AHR." (PMID 32244835, 2020). "Many asthma relevant micro-organisms induce the production of pro-inflammatory cytokine including IL-4, IL-13, and TGF-β, which are well known as contributors to the pathogenesis of asthma." (PMID 31979396, 2020). "Studies have shown that Sema4D can directly increase TGF-β1; IL-13 and TGF-β1 were decreased in a Sema4D−/− mouse model of experimental asthma." (PMID 32944173, 2020). "For example, TMEM16A was found to be expressed in airway epithelium stimulated with IL-4/IL-13, and plays an important role in mucus secretion in patients with COPD and asthma." (PMID 32514271, 2020). "Interestingly, IL-13-induced inhibition of miR-34/449 family members resulted in an altered mucociliary differentiation towards a reduced number of ciliated cells and increased number of mucous cells, suggesting a role for this miRNA family in asthma pathogenesis." (PMID 33255348, 2020). "Histopathological analyses revealed that IL-13 TG mice exhibited lung tissue inflammation, in particular eosinophilic infiltration and AHR, which are both typical features of asthma." (PMID 33046682, 2020). "The renowned type-2-high immunity occurs in almost half of asthma patients, manifested as features of eosinophilia, AHR, the elevation of IL-4, IL-5, IL-13, and Ig E in lung and blood." (PMID 33013383, 2020). "They effect Th2 cell function either directly or via innate lymphoid cells (ILCs), which in turn produce IL-5, IL-9, and IL-13, related to Th2-type CRS, asthma and AR." (PMID 32292784, 2020). "Higher serum levels of TNF-α, IL-13, IL-4, IL-10, hs-CRP and FeNO were determined in asthma patients than in healthy volunteers (P<0.05)." (PMID 33223504, 2020). "Using multiplex xMAP technology, we have further validated that the levels of the upstream cytokines of S1P signaling such as IL-13, IFN-γ, TNF-α, IL-4, IL-5, and IL-1β were increased in the serum of asthma patients." (PMID 32637407, 2020). "CLCA1 is an IL-4 and IL-13 inducible, STAT6-dependent mediator of chloride ion transport/fluid production and mucin/mucus production and is involved in asthma." (PMID 32431691, 2020). "Along with transcriptomic analysis among cohorts, including severe asthma patients, the EGFR pathway makes considerable contributions to mucus metaplasia among asthmatics, as well as the IL-13 pathway." (PMID 33217964, 2020).